IL1B (interleukin 1 beta)
Diseases named in the same sentence as IL1B in open-access papers (continued):
Sharing a sentence is not in itself a finding about the gene and the disease.
periodontitis (continued). "The IL-1β is a proinflammatory cytokine that is expressed in raised concentrations in the UWS of participants with periodontitis and peri-implant diseases." (PMID 37217913, 2023). "IL-1β is a prominent proinflammatory cytokine in periodontitis produced by numerous cells, such as macrophages, neutrophils, lymphocytes, fibroblasts, and natural killer (NK) cells." (PMID 36726081, 2023). "Compared with 10% glucose, treatment with 0.1% stevioside reduced alveolar bone absorption and osteoclasts while decreasing IL-6, TNF-α, IL-1β, and P. gingivalis in the gingiva of periodontitis mice." (PMID 37563632, 2023). "The presence of IL-1β is well described in patients with periodontitis when compared to healthy individuals (P <0.0001), but it does not show a significant difference when comparing patients with chronic and aggressive periodontitis (P =1.00)." (PMID 37026605, 2023). "A significant number of reports demonstrated a marked increase in the IL-1β levels during the periodontal inflammatory process and evidenced its importance as a good predictive biomarker of periodontitis." (PMID 36769650, 2023). "Chronic periodontitis patients consuming HN019 lozenges presented reduced levels of IL-1β and IL-8 in GCF when compared with the placebo group." (PMID 36305963, 2023). "Our results are in agreement with the vast body of literature about the relevance of salivary IL-1β as a biomarker for chronic periodontitis." (PMID 36769650, 2023). "In relation to PD, it has been shown that levels of fractalkine/CX3CL1, CX3CR1 and IL-1β in FCG are increased in patients with periodontitis compared to periodontally healthy patients." (PMID 36770741, 2023). "The accuracy of salivary IL-1β as a discriminatory biomarker of periodontitis and CHD, were illustrated by the ROC curves generated for each study group." (PMID 37974134, 2023). "Increased IL-10 can downregulate the expression of proinflammatory cytokines such as IFN-γ and IL-2/IL-1β, thereby preventing T2DM-associated periodontitis." (PMID 38098816, 2023). "Periodontitis triggers a systemic inflammatory response mediated by various factors, including C-reactive protein, interleukin 1b (IL-1b), interleukin 6 (IL-6), tumor necrosis factor alpha (TNF-α), and others." (PMID 38001437, 2023). "The majority of tissue destruction that occurs during periodontitis is attributed to IL-1β and TNF-α activity." (PMID 37102937, 2023). "Exosomes carrying down‐expressed miR‐223 from salivary enhances IL‐1β and IL‐6 expression in periodontitis." (PMID 36705422, 2023). "Clinically, the salivary concentrations of P. gingivalis, IL-1β and matrix metalloproteinase (MMP)-8 are associated with the severity of periodontitis." (PMID 38149100, 2023). "Here, we present a simple yet robust platform utilizing the MIP technique for protein imprinting to detect a biomarker, interleukin-1β (IL-1β), indicating a diagnosis of periodontitis." (PMID 38131773, 2023). "Collectively, these findings provide a strong indication of the potential role of IL-1β and TNF-α in modulating the risk of both AD and periodontitis." (PMID 36915108, 2023). "Almost 300 hosts were required to break through the obstacles of epistasis and conflicted genotypes before a significant relationship of IL1B+3954(T) with periodontitis was obtained, whereas only 15 hosts were required for this study." (PMID 37762554, 2023). "Oral treatment of patients with chronic periodontitis with tablets containing probiotic strain of L. reuteri induced a significant reduction in TNFα, IL‐1β, and IL‐17 levels." (PMID 37206247, 2023). "Some recent reports, including ours from the ARIC dental study data, suggested elevated GCF or baseline GCF levels of IL-1β or TNF-α in T2DM individuals with chronic periodontitis/gingivitis." (PMID 37893143, 2023). "IL-1β acts as a strong stimulator of bone resorption and has been identified as a salivary biomarker for discriminating periodontitis in type II diabetes mellitus." (PMID 37047282, 2023).
periodontitis (continued). "By capturing IL-1β on the electrode, the cytokine levels were quantified, and they satisfied the guidelines of periodontitis detection with reliable device-to-device uniformity in the electrochemical performance." (PMID 38131773, 2023). "Interleukin-1β (IL-1β) was the first cytokine to be specifically measured in the gingival tissue of patients with chronic periodontitis." (PMID 36769650, 2023). "There is a report of elevated level of the major autoinflammatory cytokine IL-1β in gingival crevicular fluid of patients with SCN-ELANE in a study of the correlations of periodontitis in SCN." (PMID 37350970, 2023). "Periodontitis is a prevalent chronic disease that triggers the production of proinflammatory cytokines such as IL-6, IL-8, and IL-1β as a response to bacterial infection." (PMID 39697803, 2023). "Patients with periodontitis exhibit elevated levels of salivary IL-1β, which serves as a significant indicator in gingival crevicular fluid, reflecting both the inactive and active phases of periodontitis." (PMID 38239915, 2023). "PFD inhibits alveolar bone loss and the expression of IL-1β, IL-6, and TNF-a in ligature-induced periodontitis in mice." (PMID 37240020, 2023). "In the present study, it was found that there was an increase in TNF-α and IL-1β levels in rat gingiva after periodontitis induction and systemic celastrol application suppressed this increase." (PMID 38532834, 2023). "The evidence emerging from this study associates the salivary IL-1β and RANK-L levels with an advanced stage of periodontitis, stage III/IV, and with grade C, suggesting the possible cooperative action of both in the inflammatory and bone loss events." (PMID 36769650, 2023). "This has demonstrated that subjects with gingivitis and periodontitis present a significant increase in the levels of IL-6 and other cytokines involved in the inflammatory response, such as IL-1β and TNF-α, compared to periodontally healthy subjects." (PMID 36770741, 2023). "Macrophages express a variety of inflammatory cytokines, including TNF-α, IL-1β, and IL-6 in periodontitis-affected sites." (PMID 37626627, 2023). "In periodontitis stage III/IV and grade C disease status, IL-1β and RANK-L are both present and associated with the periodontitis stage severity and progression." (PMID 36769650, 2023). "In the fifth study, significantly elevated levels of salivary cytokines, including interleukin (IL)-1β, IL-6, and tumor necrosis factor-alpha (TNF-α), were observed in periodontitis patients and strongly associated with clinical parameters." (PMID 38192959, 2023). "Elevated gene expression levels of IL-1β were also seen in both the hippocampus and the frontal cortex regions of AD mice with periodontitis." (PMID 36915108, 2023). "Compared with the control group, periodontitis mice exhibited a significant increase in proinflammatory cytokine (IL-6, IL-1β, TNF-a, IFN-β) production (p < 0.05)." (PMID 37405166, 2023). "This study evaluated and compared the benefits of probiotics and tetracycline fibers when used as adjunctive tools after scaling and root planing (SRP) on IL1β levels in type 2 diabetic patients with periodontitis." (PMID 38249256, 2023). "In periodontitis, various proinflammatory cytokines such as IL‐1β, IL‐6, and tumor necrosis factor‐α (TNF‐α) are produced." (PMID 37506160, 2023). "This study aims to compare the salivary and gingival crevicular fluid (GCF) concentrations of five cytokines: IL-1β, IL-6, IL-17A, IL-33, and Tumor Necrosis Factor-alpha (TNF-α) in patients with OSA and their association with periodontitis." (PMID 36967976, 2023). "IL-1β plays an important role in the pathology of periodontitis, and thus, we examined the effect of aging on the signal pathway responsible for IL-1β production in the presence of P. gingivalis." (PMID 37623235, 2023).
periodontitis (continued). "By comparing differentially expressed genes in neutrophils between the two groups, several inflammation‐associated genes, such as IL1B, CD44, CXCL8, and CCL4 were upregulated in the gingivae from patients with periodontitis versus healthy subjects." (PMID 37639212, 2023). "A significantly higher level of IL-1β in the stage III/IV periodontitis patients (1866.25 ± 1152.15 pg/mL) was observed compared to the healthy controls (913.25 ± 418.20 pg/mL) (p = 0.006)." (PMID 36769650, 2023). "The periodontitis I/II patients also presented higher levels of IL-1β (1429.38 ± 1037.22 pg/mL) compared to the healthy controls, albeit without statistically significant differences." (PMID 36769650, 2023). "Statistical analyses showed that nitric oxide, IL-6, IL-1B and osteoprotegerin are substances that are significantly present in patients with periodontitis (P < 0.05)." (PMID 37026605, 2023). "In mice with periodontitis, significantly increased level of IL‐1β, IL‐18, and TNF‐α was detected in gingival tissues." (PMID 37506160, 2023). "Focusing on the biomarkers present in the GCF, it was proved that IL-1 with both its types, IL-1α and IL-1β, possess great potential in distinguishing periodontitis from periodontal healthy cases." (PMID 36902030, 2023). "Similar results were published for IL-1β and IL-6, especially in patients with aggressive periodontitis." (PMID 36983201, 2023). "The serum level of IL‐1β in healthy donors, patients with mild periodontitis, and patients with severe periodontitis was determined by ELISA." (PMID 37506160, 2023). "In diabetic rats with periodontitis, incubation of osteocytes with IL-1β upregulated RANKL and downregulated OPG gene expression in static osteocytes." (PMID 40226401, 2023). "For this purpose, the changes in the level of the IL-1β inflammatory cytokine (which plays a major role in the pathogenesis of chronic periodontitis) were investigated." (PMID 35706460, 2022). "Increased levels of IL-1β in gingival crevicular fluids (GCFs) were found to correlate with the severity of periodontitis." (PMID 36359741, 2022). "The OVX rats exhibited a higher IL-1β mRNA expression; moreover, the expression of IL-1β mRNA was significantly elevated after gavage with the periodontitis salivary microbiota (p < 0.05)." (PMID 36034700, 2022). "It has been reported that TNF-α, IL-1β, IL-6, and IL-17 are highly expressed in periodontal tissues such as periodontal membranes of patients with chronic periodontitis as the expression level increases with the increase of inflammation." (PMID 35942384, 2022). "In a ligature-induced periodontitis rat model, mRNA levels of inflammatory cytokines such as IL-6, IL-1β, TNF-α, RANKL, and OPG were increased within the first week of inducing the disease." (PMID 35628390, 2022). "IL-1β production was enhanced by P. endodontalis LPS in cultured human gingival fibroblasts and monocytes from patients with periodontitis in a time- and dose-dependent manner and by F. nucleatum LPS in a dose-dependent manner." (PMID 35053286, 2022). "IL-1β levels among healthy (0.234 ± 0.299 pg/mL) and periodontitis patients (1.948 ± 1.66 pg/mL) were significantly different (p < 0.01)." (PMID 35270581, 2022). "A meta-analysis of nine papers regarding patients with periodontitis and type 2 diabetes mellitus showed significantly higher levels of IL-1β in gingival crevicular fluid in those patients compared to the ones with periodontitis alone." (PMID 36245042, 2022). "Our results showed that gavage of periodontitis saliva increased the expression of inflammatory factors, including Il-1β, Tnf-α, Cxcl1, Cxcl2, and Ccl2, in the ischemic brain in mice." (PMID 35663549, 2022). "The aim of this study was to evaluate the changes in salivary IL-1β concentration in patients with chronic periodontitis following daily consumption of green tea." (PMID 35706460, 2022).
periodontitis (continued). "As for another Prevotella soecies P. nigrescens, it was observed in in the subgingival plaque of periodontitis patients and induced host IL-1β production in dendritic cells." (PMID 36569059, 2022). "A number of retrospective studies demonstrated a correlation between polymorphisms of interleukins IL-1a, IL-1b, IL-1RN, IL-6, IL-10 as well as TNF-a and the incidence of periodontitis and peri-implant disease." (PMID 35819566, 2022). "The inflammatory factor IL-1β is involved in the pathogenesis of periodontitis and has been widely studied because it stimulates the recruitment and differentiation of osteoclasts in tissues and contributes to bone absorption during periodontitis." (PMID 35083332, 2022). "Peripheral neutrophils from periodontitis patients release excess IL-1β, IL-8, IL-6, and tumor necrosis factor (TNF-α) when stimulated by periodontal pathogens." (PMID 36294367, 2022). "LPS is a potent stimulator of inflammation, can produce proinflammatory cytokines such as TNFα, IL-6, and IL-1β, resulting in disturbance of periodontal ligament cell differentiation, and further leads to deep periodontal tissue destruction and periodontitis." (PMID 35546327, 2022). "The unstimulated whole salivary (UWS) IL-1β levels were higher in periodontitis patients compared to healthy individuals." (PMID 35270581, 2022). "Multiple studies have provided supporting evidence related to the different concentrations of IL-1β in saliva, crevicular fluid and serum especially among periodontitis patients." (PMID 35270581, 2022). "We found that among 21 DCDEGs, SLC2A3, FPR2, TREM1, and IL1B were mainly upregulated in neutrophils present in the periodontium of periodontitis patients." (PMID 36686646, 2022). "In the present study, similar IL-1β concentration was observed in initial and moderate periodontitis, however severe periodontitis showed significantly higher IL-1β levels." (PMID 35270581, 2022). "The present study findings showed that GCF IL-39, IL‐1β, and periostin total amounts were higher in patients with periodontitis and gingivitis than in the healthy controls." (PMID 35986791, 2022). "The results indicate that the daily consumption of 2 cups of green tea for a period of 6 weeks following SRP can significantly reduce the concentration of salivary IL-1β in patients with chronic periodontitis compared with the control group." (PMID 35706460, 2022). "As the dose of DhHP-6 increased, the levels of TNF-α and IL-1β were significantly lower than those in the periodontitis group." (PMID 36546940, 2022). "The interleukin-1 receptor antagonist (IL-1ra) is a natural inhibitor of IL-1, and the balance between IL-1ra and IL-1β is one of the main factors affecting chronic periodontitis (CP) and diabetes." (PMID 36430410, 2022). "Osteoclasts and expression levels of TNF-α and IL-1β were significantly increased in periodontal tissues of mice receiving periodontitis patients donated microbiome compared to these transplanted with healthy subjects donated microbiome." (PMID 35958276, 2022). "In a similar study based on a murine model of periodontitis, CEVs released from PDLSCs decreased the production of IL-18, TNF-α, and IL-1β to alleviate bone loss in periodontitis." (PMID 36585740, 2022). "It had been found that there were high levels of IL-1β, IL-6 and IL-17 in the serum of patients with periodontitis or T2D." (PMID 36131931, 2022). "This is consistent with previous studies showing that IL-1β accelerates osteoclast formation in inflammatory diseases such as periodontitis and osteomyelitis." (PMID 35682777, 2022). "The respective prevalence of IL-1A−889 and IL-1B+3953 double C/C homozygotes in periodontitis patients and in the healthy control group was 20/50 (40%) and 21/35 (60%)." (PMID 36429405, 2022).
periodontitis (continued). "Overwhelming evidence substantiates that during periodontitis, PDLSCs can stimulate macrophages to secrete inflammatory factor IL-1β by activating its endoplasmic reticulum stress, thereby mediating bone resorption and inhibiting bone tissue regeneration." (PMID 36143428, 2022). "The rigorous bioinformatics analysis performed in this study provided hints that SLC2A3, FPR2, TREM1, and IL1B are upregulated in neutrophils infiltrated in periodontium during periodontitis and mainly attributed to necroptosis, pyroptosis, and ferroptosis." (PMID 36686646, 2022). "Mature IL-1β has the capacity to up-regulate osteoclast formation and promote bone resorption in inflammatory diseases such as periodontitis and osteomyelitis." (PMID 35682777, 2022). "This is also consistent with the recent finding that enhanced myelopoiesis of HSPCs in a mouse model of β-glucan or experimental periodontitis-induced trained immunity is mediated by IL-1β." (PMID 35874771, 2022). "The present study aimed to present the salivary IL-1β concentration and periodontal inflammatory parameters among initial, moderate and severe periodontitis patients." (PMID 35270581, 2022). "The objective of the study was to evaluate the stages of pro-inflammatory cytokine IL-1β in initial, moderate and severe periodontitis." (PMID 35270581, 2022). "The pro-inflammatory cytokines TNF-α, IL-1β, and IL-6 play key roles in the occurrence and development of periodontitis." (PMID 36546940, 2022). "In the moderate periodontitis group, the concentration of IL-1β usually raised more than five times, whereas, for severe periodontitis groups, it is increased by more than seven times above the level of healthy individuals." (PMID 35270581, 2022). "All these observations lead us to predict that GM-CSF, which plays an important role in inflammatory diseases, works together with MIP-1α and IL-1β in the pathogenesis of periodontitis." (PMID 35262594, 2022). "Compared to their young counterparts, old mice suffer frequent spontaneous periodontitis, and the expression of IL-1β and TNF-α in the gingiva is significantly elevated." (PMID 36275775, 2022). "In conclusion, our study showed that SLC2A3, FPR2, TREM1, and IL1B mainly upregulated in neutrophils infiltrated in periodontium during periodontitis." (PMID 36686646, 2022). "IL-1β is a proinflammatory cytokine recognized as an important mediator in the pathophysiology of periodontitis." (PMID 35368315, 2022). "The expression levels of IL-1β and IL-6 were higher than the other two genes in the periodontitis group and periodontitis with T2DM group." (PMID 36248844, 2022). "This was also associated with a reduction of reduced serum IL-6, TNFα, and IL-1β in patients with periodontitis compared to baseline." (PMID 35874771, 2022). "This is the first study to evaluate GCF IL-39, IL-1β, and periostin levels in periodontitis, gingivitis and periodontal health to the best of the authors’ knowledge." (PMID 35986791, 2022). "TNF-α, IL-1β, and IL-6 levels in the gingival crevicular fluid of patients with periodontitis are significantly higher than those in healthy individuals, and these cytokines decreased significantly after treatment." (PMID 36546940, 2022). "Interleukin-1 beta (IL-1β) is one of the major biomarkers involved in the pathogenesis of chronic periodontitis." (PMID 35706460, 2022). "Based on the results of the present study and their connection with those achieved in a previous study, the systemic consumption of green tea can lead to improved clinical indices in patients with chronic periodontitis by reducing the IL-1β level." (PMID 35706460, 2022). "The scRNA sequencing data analysis revealed that among 21 DCDEGs, SLC2A3, FPR2, TREM1, and IL1B were mainly upregulated in neutrophils present in the periodontium of periodontitis patients." (PMID 36686646, 2022).